TIMP3 (TIMP metallopeptidase inhibitor 3)
Diseases named in the same sentence as TIMP3 in open-access papers (continued):
Sharing a sentence is not in itself a finding about the gene and the disease.
breast cancer (continued). "Co-transfection of an anti-miR-21 oligonucleotide, a renilla luciferase vector, and a pGL3-TIMP3 vector led to an increase in luciferase activity in breast cancer cell lines, indicating direct interaction of miR-21 on TIMP3 expression at the translational level." (PMID 25587717, 2015). "Tissue inhibitor of metalloproteinase 3 (TIMP3) is increased in breast cancer cell growth." (PMID 19594897, 2009). "TIMP3 may be a useful biomarker for breast cancer prognosis and drug response." (PMID 38542164, 2024). "Therefore, it is suggested that TIMP3 exhibited oncogenic role in breast cancer cells." (PMID 33653378, 2021). "We could infer that a high level of TIMP3 in breast cancer could inhibit the aggressive behavior." (PMID 34093812, 2021). "Such pro‐apoptotic mechanism mediated by TIMP3 overexpression may explain the observed anti‐proliferative and reduced anchorage‐independent growth of the breast cancer cells where ZEB1 was eliminated, thus subsequently causing upregulation of endogenous TIMP3 expression." (PMID 29744893, 2018). "We then examined whether Timp3 heterozygosity impacts mammary tumor development in both models." (PMID 25807548, 2015). "Downregulation of miR-221/222 correlates with increased TIMP3 expression and the sensitivity of MCF-7 breast cancer cells to tamoxifen." (PMID 38542164, 2024). "Reduced TIMP3 expression and increased CD44 expression strongly correlate with nodal involvement in breast cancer patients." (PMID 38542164, 2024). "After the transfection of siEmi1 mimics, the mRNA levels of the invasion-related genes Maspin, TIMP3 and RECK in breast cancer cell strains were significantly reduced." (PMID 38041032, 2023). "In breast cancer cells, miR-29c targets and downregulates DNMT3B and reduces the DNA methylation level of TIMP metallopeptidase inhibitor 3 (TIMP3)." (PMID 37298314, 2023). "This indicated that Emi1 KD can regulate the invasion-related genes Maspin, TIMP3 and RECK in breast cancer cells." (PMID 38041032, 2023). "The TIMP-3 induction is a critical epigenetic process controlled by GTPs in restoring the MMP:TIMP balance and delaying breast cancer development and invasion, according to their results." (PMID 35327559, 2022). "Strikingly, inhibition of DNMT3B reduces TIMP3 methylation levels and enhances TIMP3 protein levels, thus modulating the STAT1/FOXO1 pathway in breast cancer." (PMID 36061358, 2022). "Both TIMP-3 mRNA and protein levels are considerably increased in MCF-7 and MDA-MB-231 breast cancer cells after 72 h of treatment with 20 mM EGCG and 10 mg/mL GTP." (PMID 35327559, 2022). "Recently, miR‐181b has been found to contribute to tumour growth and metastasis by suppressing the anti‐tumour gene TIMP3 and induced EMT process in multiple cancers, including hepatocellular carcinoma and breast cancer." (PMID 33560588, 2022). "Our previous work has shown the involvement of MMP-3, MMP-9, TIMP-3, and TIMP-4 in response to radiotherapy in breast cancer patients, suggesting their utility as potential prognostic and predictive biomarkers for this pathology." (PMID 34445715, 2021). "Collectively, key observations made during the study suggest that lncRNA ROR silencing inhibited breast cancer progression by suppressing transmethylase MLL1 and TIMP3." (PMID 33653378, 2021). "Taken together, our study demonstrates that silencing of lncRNA ROR inhibits breast cancer progression via repression of transmethylase MLL1 and TIMP3, emphasizing the potential of lncRNA ROR as a novel target against breast cancer." (PMID 33653378, 2021). "We observed that BPA induced hypermethylation of TIMP3, CHFR, ESR1, and IGSF4 while HBCD induced TIMP3 tumor suppressor gene hypermethylation in MCF7 breast cancer cell line." (PMID 32466334, 2020). "BPA induced hypermethylation of TIMP3, CHFR, ESR1, and IGSF4 while HBCD induced TIMP3 tumor suppressor gene hypermethylation in MCF7 breast cancer cell line." (PMID 32466334, 2020).
breast cancer (continued). "TIMP3 and TMP4 are relevant to breast cancer biology and both were reported to be more abundant in tumor interstitial fluid collected from triple negative breast cancer patients compared to normal interstitial fluid." (PMID 33267867, 2020). "miR-21 is a well-studied oncomiR with anti-cancer targets, like PDCD4, TIMP3, and PTEN, and is overexpressed in human breast cancer tissues as compared to healthy breast tissues." (PMID 30214383, 2018). "Together, the results demonstrate a suppressive role of miR-29c by targeting the TIMP3/STAT1/FOXO1 pathway in breast cancer cell proliferation, migration and invasion, and suggest that the loss of miR-29c might be a novel biomarker related to the progression of breast cancer." (PMID 29796115, 2018). "As such, miR-221/222 knockdown upregulated TIMP3 mRNA and protein expression, which corresponded with enhanced tamoxifen-induced inhibition of cell viability in MCF-7 ER+ breast cancer cells." (PMID 30214383, 2018). "In special, TIMP-3, a potent inhibitor of ADAMTS-5, has been previously identified in breast cancer samples." (PMID 28099917, 2017). "Overall, miR-21 functions as an oncomiR and modulates tumorigenesis through regulation of genes such as ANKRD46, BCL2, TIMP3, PDCD4, PTEN, TPM1, and MASPIN in breast cancer." (PMID 27746811, 2016). "EGCG and Green tea polyphenols (GTP) mediate epigenetic activation of TIMP-3 levels, resulting in suppression of invasiveness and gelatinolytic activity of MMP-2 and MMP-9 in MDA-MB-231 and MCF-7 breast cancer cells." (PMID 27999314, 2016). "For this reason, we first analyzed the mRNA expression levels of MMP-2, MMP-9, MMP-14, TIMP-1, TIMP-2, TIMP-3 and RECK, in the same panel of five human breast cancer cell lines, but now maintained in culture until achieving 80-90% confluence." (PMID 22260435, 2012). "We then analyzed TIMP-1, TIMP-3 and RECK mRNA expression and focused on the expression of different MMP proteins in stromal fibroblasts to identify a possible role in canine mammary tumors." (PMID 21726449, 2011). "In the serum samples, promoter hypermethylation of some studied genes was correlated with clinical parameters (APC with histological grade G2; TIMP3 with late stage of breast cancer; BMP6, CST6, and TIMP3 with lymph node involvement)." (PMID 21283676, 2011). "WalBC cells exhibited expression of known markers of basal invasive human breast cancers as well as increased KRT17, KRT 14 and KRT 19, DSP, s100A4, NDRG-1, ANXA1, TK1 and AQP3 gene expression and decreased gene expression of TIMP3, VIM and TAGLN." (PMID 18179684, 2008). "Matrix metalloproteinase-1 was immunohistochemically detected in 88.3% of breast carcinomas, MMP-2 in 42%, MMP-7 in 87.4%, MMP-9 in 74%, MMP-11 in 89.3%, MMP-13 in 73.3%, MMP-14 in 90%, TIMP-1 in 95%, TIMP-2 in 87% and TIMP-3 in 82.3%." (PMID 17848954, 2007). "WDNM1, a putative breast cancer metastasis suppressor, was reduced 26-fold, and the MMP-2 inhibitor, TIMP-3, was also decreased in Comma/PDK1 cells." (PMID 16551362, 2006). "TIMP3 was proved to be a potential target of miRNAs, influencing downstream signal pathways such as proliferation, invasion survival and tumor growth in various cancers, including lung cancer 42, CRC 43 and breast cancer." (PMID 38495494, 2024). "In breast cancer cells, siRNA successfully reduced the expression of the Emi1 gene, and the expression level of the cell proliferation genes PDCD-4, FasL, PTEN and RhoB, along with invasive genes Maspin, TIMP3 and RECK, decreased significantly (P < 0.05)." (PMID 38041032, 2023). "Studies have reported that the programmed cell death receptor 4 (PDCD-4), fatty acid synthase ligand (FasL), PTEN and RhoB genes are related to the proliferative regulation of breast cancer cells and that Maspin, TIMP3 and RECK genes are related to the invasion regulation of breast cancer cells." (PMID 38041032, 2023). "In prostate and breast cancers, TET1 transactivates TIMP2 and TIMP3 to inhibit cancer invasion." (PMID 35805009, 2022).
breast cancer (continued). "MiR-21 is a miRNA overexpressed in many types of cancer, particularly breast cancer, and acts as an oncogenic marker by targeting many suppressor genes such as targeting programmed cell death 4 (PDCD4), metalloproteinase inhibitor 3 (TIMP3), PTEN, and Bcl-2." (PMID 35684480, 2022). "We aimed to elucidate the regulatory mechanism by which lncRNA ROR contributes to the progression of breast cancer in connection with MLL1 and TIMP3, with the intention of presenting a theoretical foundation for an enhanced understanding of breast cancer treatment." (PMID 33653378, 2021). "In breast carcinoma cells, ERK or p38 signalling induces TACE activation by increasing the presentation of TACE on cell surfaces and decreasing the inhibition of TACE activation by tissue inhibitor of metalloproteinase-3 (TIMP3)." (PMID 28946669, 2017). "Barx2 increased expression of both ESR1 isoforms, the estrogen-responsive genes (SOX5, RBM15 and Dynein), the tissue inhibitor of metalloproteinase (TIMP) genes (TIMP1 and TIMP3), and MMP-9, all of which promote breast cancer cell growth, survival, and invasion." (PMID 27533254, 2016). "We find that in the absence of Timp3 early breast cancer progression is delayed, but the growth of late stage carcinoma is accelerated." (PMID 25807548, 2015). "TNFR1 on mammary tumor cells is known to induce proliferation and we observed that proliferation is dampened in the absence of Timp3." (PMID 25807548, 2015). "Further, we establish TNF signaling as an important regulator of early luminal breast cancer formation and identify the requirement of Tnfr1 for mediating breast cancer suppression seen in the absence of Timp3." (PMID 25807548, 2015). "Altogether, these data show the window of breast cancer suppression to be early during tumorigenesis, yet identify a small subset of tumors that are more aggressive in the absence of Timp3 and able to progress rapidly to advanced disease." (PMID 25807548, 2015). "To study the impact of Timp3 in breast cancer development and progression we crossed Timp3−⁄− mice with MMTV-PyMT (PyMT) or MMTV-Neu (Neu) transgenic mice that represent well-accepted models of human breast cancers; all mice were on the pure FVB background." (PMID 25807548, 2015). "We next determined whether the modulation of breast cancer is a general function of the TIMP family, or if it is specific to Timp3 status." (PMID 25807548, 2015). "When the individual cell components of human breast cancer were investigated TIMP3 was not expressed in normal epithelium or in ductal carcinoma in situ (DCIS), but was overexpressed in myofibroblasts." (PMID 25807548, 2015). "Mechanistic investigations indicated that the ROR could enhance the tissue inhibitors of metalloproteinase 3 (TIMP3) transcription through demethylating the TIMP3 promoter by binding to Mixed-lineage leukemia 1 (MLL1), thus accelerating breast cancer progression." (PMID 36613528, 2022). "However, in other solid tumors, including glioblastoma, prostate, and breast cancer, the same miRNAs target important tumor suppressors - as Phosphatase and tensin homolog (PTEN), p27, p57 and TIMP metallopeptidase inhibitor 3 (TIMP3) - and function as oncogenic miRNAs." (PMID 34484116, 2021). "Even though Timp3 does not regulate immune cell influx during breast cancer onset, stromal Timp3 may influence local inflammation." (PMID 25807548, 2015). "Therefore the early suppression of mammary cancer that occurs in the absence of Timp3, and requires Tnfr1, does not involve the immune cell compartment." (PMID 25807548, 2015). "To achieve a gene panel for developing a breast cancer blood-based test we quantitatively assessed the DNA methylation proportion of 248 CpG sites per sample (total of 31,248 sites in all analyzed samples) on 10 candidate genes (APC, BIN1, BMP6, BRCA1, CST6, ESR-b, GSTP1, P16, P21 and TIMP3)." (PMID 21283676, 2011).
breast cancer (continued). "Here, we determine the role of TIMP3 through TNF in different compartments and during different stages of a breast cancer mouse model that is independent of ErbB/EGFR growth factor release." (PMID 25807548, 2015). "Next, to elucidate the involvement of the stromal microenvironment in the mammary tumor suppression found in the absence of TIMP3, PyMT cells were isolated and orthotopically transplanted into the mammary fat pads of either Timp3+/+ control or Timp3−⁄− experimental hosts." (PMID 25807548, 2015). "The T50 in MMTV-neu in the absence of Timp3 was ~76 weeks compared with ~31 weeks in Timp3+/+; MMTV-neu (calculated from Kaplan-Meier curve of the age at first detection of tumor), suggesting that Timp3−/−MMTV-neu might be another suitable model for studying aging-related breast cancer progression." (PMID 29651417, 2018).
melanoma (36 papers, 1999 to 2026). A malignant, usually aggressive tumor composed of atypical, neoplastic melanocytes. "Human cancers including melanoma show consistently that a high TIMP3 expression level is associated with a favourable patient survival (proteinatlas.org)." (PMID 31534536, 2019). "Similar to adenoviral-based overexpression of TIMP3 in melanoma cells, overexpression of TIMP3 in Cal78 cells caused activation of caspase-8, a key mediator in death receptor-mediated signaling." (PMID 23894681, 2013). "This suggests that TIMP‐3 functions as a tumour suppressor in melanoma and negatively regulates aspects of the metastatic cascade." (PMID 41546170, 2026). "In total, 43 patients were studied, whose melanoma had spread to a lymph node, to better understand the role of TIMP3 in the disease." (PMID 39199614, 2024). "Melanoma-derived exosomes carried miR21, which promoted invasion of fibroblasts by downregulation of TIMP3 expression." (PMID 35207132, 2022). "Melanoma and lymphoma cells in TIMP-3-/- mice had a higher metastatic ability, MMP-2 and MMP-9 expression levels." (PMID 36555545, 2022). "TIMP3 acts as a tumor suppressor in melanoma, inhibits cell migration, and the expression has been shown to decrease as melanoma progresses." (PMID 36230844, 2022). "A potential mechanism that explains the aggressiveness of melanoma is the overexpression of oncomiR-21 that inhibits TIMP3 which regulates the matrix metalloproteinases activity." (PMID 34199293, 2021). "This phenotype was reversed by overexpression of TIMP3, which is in line with a previous study showing that TIMP3 suppresses melanoma cell migration." (PMID 31534536, 2019). "Melanoma progression and cell migration were inhibited by TIMP-3 expression through its hypermethylation." (PMID 29467412, 2018). "A study showed that TIMP3 functions as a tumor suppressor in melanoma, and negatively regulates several aspects of the melanoma metastatic cascade." (PMID 29731768, 2018). "Reduced expression of TIMP3 was achieved by siRNA knockdown and significantly enhanced invasion of melanoma cell lines, mimicking the effects of miR-21 over-expression." (PMID 25587717, 2015). "Immunoblots of cell lysates obtained 24 hours post‐transfection revealed a decrease in the TIMP3 protein in all four melanoma cell lines transfected with pre-miR-21." (PMID 25587717, 2015). "The effects of miR-21 over-expression on melanoma invasion therefore appear to be mediated by down-regulation of TIMP3." (PMID 25587717, 2015). "Cell lines derived from different stages of melanoma development exhibited increased invasion and decreased TIMP3 protein expression when miR-21 was over-expressed." (PMID 25587717, 2015). "The finding that TIMP3 expression was decreased in melanoma cells with elevated miR-21 and increased invasiveness prompted an exploration into the influence of TIMP3 on invasion." (PMID 25587717, 2015). "Recently, it has been shown that TIMP-3, a potent inducer of apoptosis, promotes death in melanoma cells through the stabilization of death receptors and consequent activation of their apoptotic-signaling cascade through caspase-8." (PMID 26291714, 2015). "Similar results have been obtained for melanoma tumors as well where TIMP3 down-regulation by shRNA promoted angiogenesis and increased tumor size." (PMID 25587717, 2015). "Three of the four melanoma cell lines tested exhibited increased invasion when TIMP3 expression was down-regulated by siRNA as compared to the negative control‐transfected cells (WM1552c: 44.6% ± 11.8 v." (PMID 25587717, 2015). "The findings that miR‐21 expression is elevated in primary melanoma tumors and that miR-21 over-expression down-regulates TIMP3 protein expression implicates a role for miR-21 silencing of TIMP3 in the progression of melanoma." (PMID 25587717, 2015).